PUM3 (pumilio RNA binding family member 3)
Description:
Inhibits the poly(ADP-ribosyl)ation activity of PARP1 and the degradation of PARP1 by CASP3 following genotoxic stress. Binds to double-stranded RNA or DNA without sequence specificity. Involved in development of the eye and of primordial germ cells (By similarity).
Synonyms: HLA-HA8; KIAA0020; PUF-A; XTP5; PEN; PUF6; hPUF-A; HA-8
Tractability: PROTAC: ubiquitination databases record sites on it; its protein half-life has been measured.
Gene: Protein-coding gene on chromosome 9 (2,720,469 to 2,844,130, reverse strand). Ensembl gene ENSG00000080608.
Subcellular location: Nucleus, nucleolus; Nucleus, nucleoplasm; Chromosome
Subcellular location (Human Protein Atlas): Nucleoli
Gene Ontology:
Molecular function: protein binding; RNA binding; mRNA binding
Biological process: regulation of protein ADP-ribosylation; regulation of translation
Cellular component: chromosome; endoplasmic reticulum; nucleolus; nucleoplasm
Genetic constraint (gnomAD): Loss-of-function variants: 36 observed, 34.88 expected, observed/expected ratio (o/e) 1.03, 90% interval 0.79 to 1.36. The upper end of that interval is the gene's LOEUF score, 1.36, which puts it in group 5 of 6, group 1 being the genes least tolerant of losing a copy. Missense variants: 601 observed, 436.07 expected, observed/expected ratio (o/e) 1.38, 90% interval 1.29 to 1.47. Synonymous variants: 192 observed, 165.39 expected, observed/expected ratio (o/e) 1.16, 90% interval 1.03 to 1.31.
Homologues: Orthologues: chimpanzee PUM3 (99% identical), dog PUM3 (92% identical), macaque PUM3 (92% identical), pig PUM3 (92% identical), mouse Pum3 (90% identical), rat Pum3 (89% identical), rat Pum3l1 (88% identical), guinea pig Pum3 (88% identical), tropical clawed frog pum3 (65% identical), zebrafish pum3 (64% identical), Caenorhabditis elegans puf-12 (31% identical), Drosophila melanogaster peng (28% identical).
Diseases named in the same sentence as PUM3 in open-access papers:
PUM3 is named in the same sentence as 21 diseases in open-access papers, as found by Europe PMC text mining. Sharing a sentence is not in itself a finding about the gene and the disease. The quoted sentences say what the papers report.
breast carcinoma (3 papers, 2021 to 2022). "PUM3 expression has been reported to be positively associated with breast cancer progression." (PMID 33803939, 2021). "High expression of PUM3 was observed in 70% of breast cancer biopsies comprising diverse histological subtypes compared to normal breast tissues, ductal carcinoma in situ, and adjacent noncancerous tissues." (PMID 33803939, 2021).
cancer (4 papers, 2021 to 2022). A tumor composed of atypical neoplastic, often pleomorphic cells that invade other tissues. "PUM3 mRNA expression is negatively correlated with olaparib IC50 in 20 cancer types with Pearson’s r ranging from −0.63 to −0.11." (PMID 33803939, 2021). "We analyzed data from two independent groups of cancer cell lines and identified alterations in additional genes (PUM3, EEF1A1 and ELP4) that potentially increase sensitivity to olaparib." (PMID 33803939, 2021). "PUM3 mRNA expression was ranked the third strongest predictor of olaparib sensitivity, among common significant predictors from the multivariate and univariate analyses, with increased expression correlated with increased sensitivity in multiple cancer types." (PMID 33803939, 2021).
PUM3 also shares sentences with these, for which no sentence is quoted: tumor (4 papers); ductal carcinoma in situ (2); lung carcinoma (2); adenocarcinoma (1); adenoma (1); colon cancer (1); colorectal cancer (1); dental caries (1); esophageal adenocarcinoma (1); infection (1); invasive breast carcinoma (1); large cell carcinoma (1); lung adenoma (1); microphthalmia (1); non-small cell lung carcinoma (1); pancreatic ductal adenocarcinoma (1); sarcomatoid carcinoma (1); squamous cell carcinoma (1); trigonocephaly (1).